IL6 (interleukin 6)
Diseases named in the same sentence as IL6 in open-access papers (continued):
Sharing a sentence is not in itself a finding about the gene and the disease.
cerebral malaria (25 papers, 2010 to 2025). A sequestration of Plasmodium falciparum in the brain, which can cause coma and/or seizures. "Elevated levels of IFN-γ, TNF, IL-12, IL-6, IL-1β, and IL-10 are initially protective, although excessive serum levels of these cytokines are associated with cerebral malaria pathology." (PMID 22336003, 2012). "A major outcome of monocyte activation is elaboration of inflammatory mediators such as TNFα and IL-6, each of which has been shown to be necessary or associated with cerebral malaria." (PMID 20454664, 2010). "Additionally, we quantified IL-6 because its increase has been associated with more severe symptoms, and cerebral malaria." (PMID 36237427, 2022). "IL-6 is repeatedly described as highly induced in the CNS during times of neuroinflammation, such as viral meningitis, murine cerebral malaria, systemic lupus, and HIV-1." (PMID 40985448, 2025). "In the case of experimental cerebral malaria, the authors found a higher mRNA expression of the pro-inflammatory cytokines IL-2, IL-6, IL-10, IL-17, IFN-γ, and TNF in the serum, hippocampus, and frontal cortex in mice infected with Plasmodium berghei." (PMID 39057789, 2024). "Increasing pro-inflammatory cytokines like TNF-α and IF-γ, as well as certain interleukins like IL-6, IL-10, and IL-12, is probably a key to the etiology of cerebral malaria." (PMID 39204168, 2024). "Children with cerebral malaria had higher cerebrospinal fluid levels of IL-6, IL-8, granulocyte-colony stimulating factor (G-CSF), TNF-α, and the IL-1 receptor antagonist than those with noncerebral malaria." (PMID 36668942, 2023). "Other inflammatory cytokines, such as interferon gamma (IFN-γ), interleukin-6 (IL-6), and IL-1β, are also elevated in adults and children with cerebral malaria, with circulating concentrations ranging between 0.01 and 1 ng/mL." (PMID 36036514, 2022). "This notion changed with evidence of IL-6 induction in pediatric cerebral malaria cases." (PMID 31878288, 2019). "Here, plasma and cerebral TNFα and IL-6 production was markedly diminished by TRPV1 ablation, thus evidencing, once more, that TRPV1 signaling is involved in the tissue damage associated with cerebral malaria." (PMID 31223430, 2019). "Additionally, ARM may inhibit the activation of immune cells, such as microglia and macrophages, which are major sources of IL-6 production in cerebral malaria." (PMID 38675426, 2024). "As IL-6 is a key mediator of pro-inflammatory signalling pathways, by targeting IL-6, either through inhibition of its production or blockade of its signalling pathways, it may be possible to reduce the overall inflammatory response in cerebral malaria." (PMID 38675426, 2024). "Mice infected with WT PbANKA parasites developed experimental cerebral malaria (ECM) and died around day 8 post-infection whereas mice injected with either IL-6 Tg-PbANKA/LISP2 line 1 or line 2 survived." (PMID 37143657, 2023). "Cerebral malaria is the most severe form of infection with Plasmodium falciparum characterized by a highly inflammatory response (IFN-γ, IL-1β, TNF-α, iNOS, and IL-6), which contributes to severity of the disease." (PMID 34975479, 2021). "In the context of cerebral malaria, ARM has been shown to possess anti-inflammatory properties, which may contribute to its ability to reduce the expression of interleukin-6 (IL-6)." (PMID 38675426, 2024). "The degree of brain swelling was independent of plasma levels of IL-1β, IL-6, IL-8, and IL-10 in children with cerebral malaria, while IL-12 and TNF were elevated in patients with more severe edema." (PMID 33391257, 2020). "On the other hand, the role of IL-6 in the development of cerebral malaria has not been well elucidated, as well as the role of IL-10, which may have double features during malaria infection." (PMID 31878288, 2019). "Mice infected with IL-6 Tg-PbANKA/UIS4, like WT PbANKA infected mice, developed experimental cerebral malaria and did not survive." (PMID 37143657, 2023).
cerebral malaria (continued). "Serum TNF, IFN-γ, IL-1β, IL-6, and IL-10 did not vary based on either TLR2 Δ22 or GTn genotype in children with cerebral malaria." (PMID 22336003, 2012).
Hodgkins lymphoma (25 papers, 2009 to 2026). A heterogeneous group of malignant lymphoid neoplasms of B-cell origin characterized histologically by the presence of Hodgkin and Reed-Sternberg (HRS) cells in the vast majority of cases. "In accordance with our data, an association with IL-6 levels and survival in Hodgkin lymphoma has been recognized almost twenty years ago." (PMID 23145841, 2012). "The serum concentrations of cytokines such as interferon, tumor necrosis factor-α, and IL-6, which activate macrophages, were possibly elevated exclusively in the lymph nodes and spleen containing Hodgkin lymphoma cells." (PMID 39974298, 2025). "Elevation of serum IL-6 levels was reported in a patient with Hodgkin’s lymphoma who developed TLS after chemotherapy." (PMID 37215107, 2023). "IL-6 levels are augmented in patients with Hodgkin lymphoma and are correlated with a poor prognosis." (PMID 30065253, 2018). "The shed form of CD163 is upregulated in a large range of inflammatory diseases and Hodgkin lymphoma, is induced by anti-inflammatory factors such as IL-6 and IL-10, and is known to be upregulated in PCNSL." (PMID 29299134, 2017). "Tumor necrosis factor-α and interleukin-6 are expressed in Reed-Stemberg cells from patients with Hodgkin lymphoma." (PMID 26046344, 2015). "Hodgkin's lymphoma is clinically characterized by symptoms resembling those of chronic infectious diseases and levels of interleukin-6 are high in untreated patients." (PMID 19238200, 2009). "Of note, high IL-6 expression is associated with poor prognosis in both non-Hodgkin’s and Hodgkin’s lymphoma." (PMID 34576335, 2021). "Further, MNX1 was found to activate IL-6 expression in Hodgkin lymphoma cells through regulating PI3K signaling, which might participate in mediating inflammatory response." (PMID 32850524, 2020). "Elevated levels of IL-1β, TNF-α, IL-6, IL-8, and IL-10 are detected in the serum of patients with EBV-associated diseases, while a less favorable outcome correlates with increases of IL-6 and IL-10 in Hodgkin's lymphoma." (PMID 23346088, 2012). "We analyzed the distribution of circulating B-lymphocytes and the level of the activating cytokines IL6, IL10 and BAFF in 38 patients with HIV-related Hodgkin’s lymphoma during a 2-year follow-up." (PMID 35008292, 2021).
Lymphadenopathy (25 papers, 2013 to 2025). Enlargement (swelling) of a lymph node. "This case suggested that increased serum IL-6 concentration might play an important role in lymphadenopathy and PBC associated with RA/lSSc." (PMID 24839573, 2014). "Elevated levels of IL‐6 result in various manifestations such as lymphadenopathies, hepatosplenomegaly and polyclonal hypergammaglobulinemia." (PMID 39252436, 2024). "IL‐6 seems to be a key cytokine involved in various manifestations such as lymphadenopathies, hepatosplenomegaly, and polyclonal hypergammaglobulinemia." (PMID 39252436, 2024). "Serum IL-6 level usually correlates with the degree of lymph node hyperplasia, hypergammaglobulinemia, acute-phase protein levels, and clinical characteristics." (PMID 32399323, 2020). "Fas mutation in MRL/MpJ mice significantly increased serum IL-6 and tumour necrosis factor-α (TNF-α) levels due to systemic autoimmunity and massive lymphadenopathy associated with the proliferation of aberrant T cells." (PMID 32686763, 2020). "A plausible hypothesis is that lymphadenopathy reflects heightened systemic inflammation and immune activation driven by excessive cytokine production (e.g., IL-1β, IL-6, IL-18)." (PMID 39797367, 2025). "As an example, interleukin 6 (IL6) is an approved drug target for giant lymph node hyperplasia." (PMID 30736745, 2019). "Unlike UCD, MCD presents with multiple peripheral lymphadenopathies and systemic symptoms such as fever, night sweats, weight loss, or fatigue, and its manifestation essentially results from proinflammatory hypercytokinemia of interleukin-6 (IL-6)." (PMID 35992883, 2022). "Treatment with pegylated-liposomal doxorubicin rapidly resolved the KS lesions, reduced lymphadenopathy from MCD, and sharply lowered both viral load and IL-6 levels." (PMID 41008782, 2025). "CD can present with a solitary enlarged lymph node (unicentric CD, UCD) or with multicentric lymphadenopathy (MCD), constitutional symptoms, cytopenias, and multiple organ dysfunction due to an interleukin-6 driven cytokine storm." (PMID 32028407, 2020). "For patients with fever of unknown etiology and lymphadenopathy, after excluding HLH or MAS, serum IFN-γ > 8.56 pg/mL and IFN-γ/IL-6 ratio > 0.45 may highly suggest the diagnosis of KFD." (PMID 37608293, 2023). "Similarly, IL-6 (P=0.0006), IL-10 (P=0.001), IL-12p40 (P=0.03), TNFα (P≤0.002) and chemokines MIP-1β (P<0.0001) and MCP-1 (P=0.002) (but not IL-1β, IL-13 and G-CSF) were significantly elevated in Tg mice at late stages of lymphadenopathy (Tg L) relative to WT controls." (PMID 23985023, 2013).
metastatic melanoma (25 papers, 1994 to 2025). A melanoma that has spread from its primary site to another anatomic site. "In contrast, there is a large body of evidence that PD-1 and CTLA-4 inhibitors cause systemic inflammation in metastatic melanoma, including higher circulating levels of IL-1ra, IL-6, and IL-17, which are associated with irAEs such as colitis and dermatitis." (PMID 33302472, 2020). "There is evidence that the E2F1-STAT3/IL-6 axis fosters an immunosuppressive microenvironment by promoting Th2 and inhibiting Th1 cell infiltration in primary and metastatic melanoma." (PMID 40954493, 2025). "Targeting cytokines such as IL-6 and IL-15 is currently being evaluated in clinical trials in combination with immune checkpoint-blocking antibodies for the treatment of metastatic melanoma." (PMID 38928238, 2024). "Clinical data from TCGA demonstrated that elevated E2F1, STAT3, and IL-6 correlate with infiltration of Th2, while simultaneously blocking Th1 in primary and metastatic melanomas." (PMID 39544930, 2024). "In past large randomized trials, higher IL-6 and CRP were associated with shorter overall survival in patients with metastatic melanoma who received ICI or chemotherapy." (PMID 38952546, 2024). "The prognostic and predictive role of IL-6 in patients with metastatic melanoma treated with checkpoint inhibitor immunotherapy has been investigated in three large phase II/III randomized trials." (PMID 36823670, 2023). "In particular, IL-6 has been proposed as a prognostic biomarker in patients with metastatic melanomas and it can be used to evaluate the efficacy of therapeutic treatments." (PMID 36639824, 2023). "In contrast, the increased plasma concentration of IL6 and IL8 is linked with the worse survival for patients with metastatic melanoma." (PMID 35327461, 2022). "There are currently phase Ib-II clinical trials evaluating anti-IL-6 blockade combined with ipilimumab and nivolumab in patients with unresectable or metastatic melanoma (NCT03999749) or with anti-Her2 antibodies in Her2 amplified breast cancer (NCT03135171)." (PMID 35743911, 2022). "We found that IL6 plays a role in inducing the release of liver GSH in models of metastatic melanoma." (PMID 34943110, 2021). "As previously suggested concerning murine models of metastatic melanoma, we found that IL6 also promotes the release of GSH from the liver in the two ALS models assayed." (PMID 34943110, 2021). "We found that stimulation of the human metastatic melanoma 1205Lu cells with recombinant IL-1β increased IL-6 after 24 hours compared to the vehicle-treated control cells (p<0.001)." (PMID 34531850, 2021). "Higher circulating levels of CRP and IL-6 prior to treatment with ICIs appear to be poor prognostic indicators among patients with metastatic melanoma, although evidence is mixed." (PMID 33302472, 2020). "IL‐6 has been shown to promote invasive migration of parental BRAFi‐sensitive metastatic melanoma cells." (PMID 30582770, 2019). "As was observed with the MCA-OVA, OT-II cells primed with peptide-pulsed DCs were ineffective for metastatic melanoma in aged IL-6+/+ mice compared with those in young IL-6+/+ or IL-6−/− mice." (PMID 25850032, 2015). "Thus, diminished secretion of E/P-selectins and ICAM-1 in the keratinocytes can be related to the inhibition of IL6 secretion observed upon the incubation with metastatic melanoma EVs." (PMID 35327461, 2022). "In this context, metastatic melanoma may induce chronic high level of IL6, which can both confer aggressiveness and compromise the immune-inflammatory regulation, impairing the immune response elicited by CTLA4 blockade." (PMID 29642948, 2018). "Similarly, significantly increased levels of serum IL-6 in malignant metastatic melanoma patients have been found to be correlated to the tumor burden in these patients." (PMID 23175106, 2013).
metastatic melanoma (continued). "Among patients with metastatic melanoma treated with immune checkpoint-blocking antibodies, IL-6 is a significant prognostic factor for survival: elevated baseline and on-treatment levels of IL-6 correlate with worsened overall survival across multiple randomized studies." (PMID 38928238, 2024). "The increased IL-6 levels observed in metastatic melanoma patients may have a beneficial role." (PMID 37895833, 2023). "In contrast to IL-6 production, treatment with tumor cell-derived supernatants generally did not modify the TNFα secretion by moDCs, but the supernatant of WM1617 metastatic melanoma cell line induced significantly increased TNFα production." (PMID 36194602, 2022). "In clinical studies of patients with metastatic melanoma treated with the anti-CTLA-4 monoclonal antibody ipilimumab, lower IL-6 serum levels have been correlated with increased survival." (PMID 35743911, 2022). "Interleukin 6 and C-reactive protein (CRP) were determined prior to IL-2 therapy in sera from metastatic melanoma patients." (PMID 8180022, 1994). "Enhanced level of mRNA coding the IL6, IL10, IL12, sICAM-1, sICAM-3, sPECAM-1, and CD40L proteins, whose secretion by the keratinocytes was inhibited by EVs, correlated with the better survival prognosis of the patients with metastatic melanoma." (PMID 35327461, 2022). "In line with this, the bioinformatic analysis of the TCGA database revealed that the high expression of the genes coding IL6, IL10, IL12, ICAM-1, ICAM-3, PECAM-1, and CD40L in tissues of patients with metastatic melanoma correlates with the better survival prognosis." (PMID 35327461, 2022). "Analyzing immunosuppressive characteristics of metastatic melanoma patients before the treatment, we observed that some patients were characterized by increased MDSC frequency and immunosuppression as well as by high concentrations of MDSC-related cytokines (IL-6, IL-8)." (PMID 36860876, 2023). "In addition, a significant serum IL-6 levels increase in patients with psoriasis-afflicted or other ICIs-related toxicities after nivolumab treatment while decreases were observed in non-afflicted metastatic melanoma patients." (PMID 33123120, 2020). "In line with previous reports, the serum levels of IL-6 and CXCL8 were not significantly elevated among AP and RP patients, as opposed to higher levels observed in metastatic melanoma patients, similar to previously reports." (PMID 26909604, 2016).
myxoma (25 papers, 2008 to 2025). A benign soft tissue neoplasm characterized by the presence of spindle and stellate cells, lobulated growth pattern, and myxoid stroma formation. "An enzyme-linked immunosorbent assay (ELISA) showed that the myxoma cells spontaneously secreted IL-6 into the culture medium." (PMID 38396907, 2024). "Excessive IL-6 production is associated with local myxoma growth, and frequent recurrence, and literature reports a relationship between distant myxoma metastases and PS." (PMID 37197119, 2023). "moyamoya angiographic changes in myxoma may be linked to repeated embolism, post-embolic arterial wall degradation, and subsequent inflammatory response mediated by interleukin-6." (PMID 38817499, 2024). "However, elevated IL-6 has been associated with constitutional symptoms and tumor burden in myxoma patients and may have utility in monitoring recurrence." (PMID 40630762, 2025). "Interestingly, while the cytokine IL-6, known to be associated with cardiac myxomas, is often correlated with lower hemoglobin levels in the context of COVID-19, no substantial data exist on its direct impact on embolism in myxoma patients." (PMID 40548199, 2025). "In addition, other investigators reported that IL-6 secreted by the cardiac myxoma caused the mediastinal lymphadenopathy, and resection of the myxoma tissue resulted in resolution of mediastinal lymphadenopathy together with a reduction in IL-6 levels to normal levels." (PMID 38396907, 2024). "Constitutional symptoms are related to the overproduction of interleukin 6, which plays a major role in the proliferation of myxoma cells." (PMID 40034884, 2025). "Immunocytochemical staining showed positive immunoreactivities for IL-6, IL-6R, and gp130 in the cultured myxoma cells." (PMID 38396907, 2024). "IL-6 was markedly increased in the supernatant of the myxoma cells compared with control culture media." (PMID 38396907, 2024). "Myxoma cells were cultured, and an antibody array assay showed that a conditioned medium derived from the cultured myxoma cells contained increased amounts of IL-6." (PMID 38396907, 2024). "The presence of ligand and receptors of IL-6 in the myxoma cells supports the idea that both the classic and trans-signaling pathway are involved in the signal transduction system of IL-6 in the human cardiac myxoma cells." (PMID 38396907, 2024). "In the present study, myxoma cells were treated with exogenous IL-6 + sIL-6R, and mRNA was isolated and analyzed by real-time PCR." (PMID 38396907, 2024). "Studies have noted that these symptoms are a product of interleukin-6 production by the myxoma and resolve following resection." (PMID 39735071, 2024). "The present antibody array assay analysis demonstrated that, in addition to IL-6, the culture supernatant of myxoma cells incubated for 7 days included considerable amounts of molecules such as MCP-1, GM-CSF, and PDGF-BB." (PMID 38396907, 2024). "The immunofluorescence signal of phosphorylated STAT3 located in the nuclei of the myxoma cells after incubation with IL-6 + sIL-6R for 30 min was compared with the untreated control cells." (PMID 38396907, 2024). "Transfection of STAT3 significantly attenuated spontaneous IL-6 secretion from the myxoma cells compared with control-scrambled siRNA transfection." (PMID 38396907, 2024). "The secretion of IL-6 from the myxoma cells was significantly inhibited by the treatment with AG490 (JAK2 inhibitor, 100 μmol/L), piceatannol (STAT1/3 inhibitor, 100 μmol/L), LLL12 (STAT3 inhibitor, 10 μmol/L), and Ly294002 (PI3K/Akt inhibitor, 30 μmol/L)." (PMID 38396907, 2024). "The addition of antibody against IL-6R or gp130 reduced the secretion of IL-6 from the myxoma cells." (PMID 38396907, 2024). "Real-time PCR revealed that stimulation with IL-6 + soluble IL-6R (sIL6R) significantly increased IL-6 mRNA in the myxoma cells." (PMID 38396907, 2024).